GNAS (GNAS complex locus)
Diseases named in the same sentence as GNAS in open-access papers (continued):
Sharing a sentence is not in itself a finding about the gene and the disease.
thyroid cancer (15 papers, 2012 to 2025). "The mutation p.R201C (in exon 8) is the most prevalent point mutation in GNAS, which was identified in many cancers, including thyroid cancer." (PMID 36151521, 2022). "In human thyroid cancer, driver mutations in the GNAS gene were also identified, but usually at a low prevalence." (PMID 36151521, 2022). "The marker in the GNAS gene has also been included in a diagnostic panel of thyroid cancer (ThyroSeq)." (PMID 36151521, 2022). "In 492 human thyroid carcinoma samples from the TCGA, mutations in the GNAS gene were detected in only 2 patients and these 2 mutations in the GNAS gene were at different locations from GNAS p.A204D." (PMID 36151521, 2022). "LOI of the GNAS gene has been reported to be associated with increased risks of multiple cancers including thyroid cancer, skin cancer, osteosarcoma and neurofibromatosis." (PMID 34906185, 2021). "Current literature shows that the GNAS mutation is an oncogenic driver in many tumor types such as pancreatic adenocarcinoma, adrenocortical carcinoma, and thyroid carcinoma; however, current data are limited on the role of GNAS mutations in SCC of the lung." (PMID 33936872, 2021). "The results of this study yield new insights on WDTC, showing that inherited variants in the APC and GNAS genes can play a role in the etiology of thyroid cancer." (PMID 28410400, 2017). "The difference in the prevalence of GNAS mutations in humans and our dog samples could suggest a species difference in the driver mutations for thyroid cancer between GLPs and humans." (PMID 36151521, 2022). "There is evidence suggesting that LOI of the guanine nucleotide-binding protein, alpha-stimulating complex locus (GNAS) gene may increase the risk of thyroid cancer, osteosarcoma, skin cancer, and neurofibromatosis." (PMID 32448196, 2020). "In addition, activating mutations of [i]GNAS[/i] have been identified in adrenal hyperplasia, ovarian cysts, thyroid carcinomas, adrenocortical, pituitary, renal and Leydig cell tumors." (PMID 22985616, 2012). "Moreover, thyroid cancer had been described in a few cases of MAS with demonstrated GNAS mutation in molecular studies, suggesting that MAS might predispose patients to thyroid carcinomas." (PMID 33557156, 2021). "This is consistent with IPA analysis results that 78 DEPs including GNAS were closely related to thyroid carcinoma and cancer of secretory structure." (PMID 33299887, 2020). "These DEPs were involved in cancer, including thyroid carcinoma, head and neck carcinoma, and cancer of secretory structure, in which CLU, GNAS, and PKM played an indirect role in the occurrence and development of cancer." (PMID 33299887, 2020).
Pancreatic cysts (14 papers, 2014 to 2025). A cyst of the pancreas that possess a lining of mucous epithelium. "They found that GNAS in ctDNA from peripheral blood of patients with pancreatic cysts was significantly higher in those with IPMN so this mutation can serve as a specific IPMN predictor for differentiating it from the various PCNs." (PMID 34884643, 2021). "In conclusion, we revealed that the detection of GNAS mutations in cfDNA from peripheral blood of patients with pancreatic cysts is a highly specific indicator for IPMNs, specifically the intestinal subtype." (PMID 33082481, 2020). "Further analysis of GNAS mutations and the addition of GNAS analysis to KRAS mutation findings remain controversial in pancreatic cyst diagnosis." (PMID 32050465, 2020). "GNAS mutations have also been previously reported in IPMN cases that had pancreatic cysts with a detection rate of 41–66% from resected tissues, pancreatic cyst fluids, or secretin-stimulated pancreatic juice collected from the duodenum." (PMID 24897499, 2014). "However, KRAS and/or GNAS detection alone in pancreatic cyst fluid has been found to be highly sensitive and specific (100% and 96%, respectively) for the diagnosis of branch duct IPMN." (PMID 36359417, 2022). "The addition of GNAS to pancreatic cyst fluid KRAS testing has been shown to increase the diagnostic accuracy of IPMN identification from 66 to 80.7%, though this does not achieve a statistically superior result to KRAS testing alone (p > 0.05), which has a diagnostic accuracy of 76.6%." (PMID 33673153, 2021). "The guanine-nucleotide-binding protein-alpha stimulating (GNAS) and the Kirsten rat sarcoma viral oncogene homolog (KRAS), an oncogene and proto-oncogene, respectively, have also been identified as commonly mutated in pancreatic cyst fluid." (PMID 32050465, 2020). "Pancreatic cyst fluid can also be analyzed for CEA, amylase, cytology and molecular markers (e.g., KRAS and GNAS)." (PMID 33808853, 2021). "Accuracy of the mutation detection was analyzed by PCR amplifying DNA from pancreatic cyst fluid by analyzing 30 samples (15 negative and 15 positive) each for the KRAS and GNAS mutations, followed by sequencing on an ABI 3130 genetic analyzer and two ABI 3730 genetic analyzer instruments." (PMID 38472986, 2024).
diabetes (13 papers, 2008 to 2025). "Many risk factors have been shown to increase the incidence of these neoplasms including diabetes mellitus, as in our case, chronic pancreatitis, family history of pancreatic ductal adenocarcinoma, and mutations in GNAS and KRAS genes." (PMID 32900376, 2020). "The epigenetic modification of GNAS is sensitive to environmental condition and the function of GNAS is associated with diabetes, hypertension and other metabolic diseases." (PMID 23844573, 2013). "Partial correlations between changes in APOA-I, GNAS and changes in metabolic measures after controlling for age, gender and family history of diabetes (N = 80)." (PMID 24710015, 2014). "GNAS is important for β-cell insulin secretion, with reduced expression observed in pancreatic islets from individuals with type 2 diabetes and in urine from individuals with diabetes." (PMID 38904047, 2024). "Examples include as follows: (a) NEUROD1 which encodes a transcription factor that is involved in the development of the endocrine cell lineage and has been implicated in monogenic diabetes, (b) PRKCB involved in insulin resistance and (c) GNAS, implicated in beta-cell proliferation." (PMID 30914061, 2019). "Specifically, methylation changes occurs in genes related to intermediate metabolism, diabetes, inflammation, and signal transduction process, such as CPT1B and GNAS, which are specifically involved in acyl-carnitine process in mitochondria, and glucose and energy regulation, respectively." (PMID 29295516, 2017).
Hypertension (13 papers, 2008 to 2025). The presence of chronic increased pressure in the systemic arterial system. "In white subjects, a common silent polymorphism (393C > T) involving a change in codon 131 from ATT (Ile) to ATC (Ile) in the GNAS gene was linked to hypertension and the BP response to β-Blocker therapy." (PMID 35433877, 2022). "Another novel KD GNB1 in “Insulin regulation” encodes a G protein β subunit, multiple mutations of which were found to affect the protein interface that binds Gα subunits (GNAS), which has been genetically and clinically associated with hypertension." (PMID 30931314, 2019). "Our search revealed both known KDs showing connections to hypertension or relevant conditions in one or more types of studies (99 KDs; such as GNAS, SLC2A3, IRS1, ADM, and SERPINE1) and relatively novel KDs in BP studies (such as SPTBN1 and GNB1)." (PMID 30931314, 2019). "GWAS variant rs16982520, located within ZNF831, is associated with hypertension, systolic blood pressure and mean arterial pressure and interacts directly with EDN3 and four direct interactors of the putative regulatory region (GNAS, RP4-614C15." (PMID 38885195, 2024).
Hypocalcemia (11 papers, 2011 to 2025). An abnormally decreased calcium concentration in the blood. "It is interesting that the category of the loss-of-function GNAS variants (to which our mutation belongs) also showed a higher incidence of hypocalcemia and hyperphosphatemia." (PMID 39456695, 2024). "PTH resistance is characterized by elevated parathyroid hormone (PTH) levels, hypocalcemia, hyperphosphatemia and it is classically associated with GNAS locus genetic or epigenetic defects." (PMID 35846276, 2022). "Patients with PHP1A develop PTH resistance and associated hypocalcemia and hyperphosphatemia, features attributable to imprinted expression of GNAS." (PMID 23284784, 2012). "This delay in imprinting of GNAS in proximal renal tubules leads to delay in PTH resistance and also to the clinical and biochemical expression of its associated manifestations such as hypocalcemia and seizures." (PMID 27467896, 2016).
myxoma (11 papers, 2012 to 2025). A benign soft tissue neoplasm characterized by the presence of spindle and stellate cells, lobulated growth pattern, and myxoid stroma formation. "Even though cytogenetic information cannot be used for the diagnosis of myxomas, we found an association between karyotypes and specific GNAS pathogenic variant." (PMID 38317844, 2024). "The two methods used, i.e., direct cycle Sanger sequencing (BigDye Direct Cycle Sequencing Kit) and NGS panel (Ion AmpliSeq Cancer Hotspot Panel v2) gave identical results detected GNAS pathogenic variant in 83% of the examined myxomas." (PMID 38317844, 2024). "In 26% of the myxomas which carried GNAS pathogenic variants, both methods detected pathogenic variants other than the common “hotspot” of p.R201C and p.R201H." (PMID 38317844, 2024). "Detecting pathogenic variants within the GNAS gene in intramuscular myxoma can be difficult due to the poor cellularity of the tumor and the low frequency of mutated alleles, which was found to be between 5% and 30%." (PMID 38317844, 2024). "The average variant frequency (VAF) of the myxomas with GNAS mutation was 10.67% (ranging from 2.35% to 27.91%)." (PMID 38791144, 2024). "So far, mutations in GNAS exon 8 on positions 601 and 602 have been described in intramuscular myxoma." (PMID 38791144, 2024). "In challenging cases, GNAS mutation analysis is of diagnostic value in daily routine to differentiate intramuscular/cellular myxoma from malignant mimickers." (PMID 38791144, 2024). "GNAS also has a low range of pathogenic allele frequencies in intramuscular myxomas, ranging between ∼ 5–30%." (PMID 38317844, 2024). "Clinicopathological data, karyotypes, and status of pathogenic variants of the GNAS gene on the intramuscular myxomas." (PMID 38317844, 2024). "Intramuscular myxomas tumors have low allele frequencies of GNAS pathogenic variants and in our investigation, we found an average allele frequency of 13%." (PMID 38317844, 2024). "In conclusion, our results support the previous finding that intramuscular cellular myxoma harbors GNAS mutation in up to 90% of cases, distinguishing it from MFSs." (PMID 38791144, 2024). "A useful tool for the diagnosis of intramuscular myxomas is that intramuscular myxomas often carry a somatic GNAS pathogenic variants." (PMID 38317844, 2024). "Thereafter, many studies have shown GNAS pathogenic variants occurring frequently in sporadic intramuscular myxomas." (PMID 38317844, 2024). "GNAS mutations can be used as good diagnostic tool to distinguish intramuscular / cellular myxoma from low-grade myxofibrosarcoma, especially on biopsy material." (PMID 30111377, 2018). "We were able to demonstrate that the detection of GNAS mutations is more common in intramuscular / cellular myxoma than reported in the past." (PMID 30111377, 2018). "Next generation sequencing for determining GNAS mutation status on small biopsies or diagnostically challenging cases facilitates the diagnosis of intramuscular / cellular myxoma and separates this tumor entity from its mimics." (PMID 30111377, 2018). "Our findings demonstrate that GNAS mutations are more common in intramuscular / cellular myxomas, than had been reported in literature in the past." (PMID 30111377, 2018). "Molecular genetic analyses of the GNAS gene (20q13) have revealed activating missense mutations, R201H and R201C, in exon 8 at codon 201 of the GNAS gene in both solitary intramuscular myxoma and the multiple intramuscular myxomas of Mazabraud syndrome." (PMID 28160572, 2017). "Apart from myxomas, R201C, R201H, and Q227R mutations of GNAS protein were found also in a variety of other neoplasms such as tumors of the kidney, thyroid, pituitary, leydig cells, adrenal cortex, and large bowel." (PMID 28160572, 2017). "Depending on the method, GNAS pathogenic variants were found in ∼30–80% of intramuscular myxomas." (PMID 38317844, 2024).
myxoma (continued). "Secondly, the presence of the rare pathogenic variants R201S, p.R201G and p.Q227E in 26% (5 out of 19) of myxomas with GNAS pathogenic variants shows that methodologies designed to detect only the common “hotspot” of p.R201C and p.R201H will give false negative results." (PMID 38317844, 2024). "Thus, assays targeting only these pathogenic variants, p.R201C and p.R201H, such as pyrosequencing, quantitative real-time PCR, and digital PCR should be used with caution for the detection of GNAS pathogenic variants in intramuscular myxomas." (PMID 38317844, 2024). "Cellular myxoma is a benign soft tissue tumor frequently associated with GNAS mutation that may morphologically resemble low-grade myxofibrosarcoma." (PMID 38791144, 2024). "In addition to p.R201H and p.R201C, which were detected in 44% and 31% of the samples respectively, four other GNAS pathogenic variants were found in intramuscular myxomas; p.R201S, p.R201L, p.R201P and p.Q227R." (PMID 38317844, 2024). "However, they found GNAS pathogenic variants in 17 out of 28 (61%) intramuscular myxomas with COLD-PCR followed by pathogenic variant-specific restriction enzyme digestion." (PMID 38317844, 2024). "More than 90% of intramuscular myxomas have a GNAS activating point mutation (WHO)." (PMID 39410565, 2024). "On a molecular level, myxomas show recurrent GNAS mutations in up to 90% of cases." (PMID 38791144, 2024). "Pathogenic variants in the GNAS gene were detected in 19 out of 22 myxomas (86%)." (PMID 38317844, 2024). "Therefore, our data highly suggest that more intramuscular / cellular myxomas show a GNAS mutation than initially reported in the literature." (PMID 30111377, 2018). "Notably, juxta-articular myxoma and cardiac myxoma also lack GNAS driver mutations." (PMID 30736805, 2019). "Here we present our karyotypic analysis of intramuscular myxomas as well as analysis of the GNAS gene in five of the tumors." (PMID 28160572, 2017). "Of note, none of the GNAS mutations in MFSs involved the R201 locus that characterizes intramuscular myxoma." (PMID 30018380, 2018). "Additionally, GNAS pathogenic variants are absent in low-grade myxofibrosarcoma, which can be used as a malignant differential diagnosis to intramuscular myxomas." (PMID 38317844, 2024). "Our study shows the diagnostic potential and the limitations of molecular analysis in cases where morphology and immunohistochemistry are not sufficient to distinguish cellular myxoma from myxofibrosarcoma, particularly regarding GNAS wild-type tumors." (PMID 38791144, 2024).
pancreatic ductal adenocarcinoma (11 papers, 2013 to 2025). An infiltrating adenocarcinoma that arises from the epithelial cells of the pancreas. "Recent experiments have begun to decipher the functional consequences of the GNAS p.R201C mutation in pancreatic ductal adenocarcinomas, where it modulates KRAS p.G12V initiated neoplasia." (PMID 31337866, 2019). "Among these mutations, K-ras mutation could be found in both pancreatic duct adenocarcinomas and IPMNs, but GNAS mutation at exon 8 (Arg201Cys or Arg201His) is specifically detected in IPMNs." (PMID 34674710, 2021). "Animal studies indicate that concurrent G-protein αs (GNAS) and KRAS mutations characterize pancreatic ductal adenocarcinomas (PDAs) arising from IPMNs, associated with the induction of lipid remodeling and fatty acid oxidation." (PMID 41181742, 2025). "The GNAS mutation is not observed in conventional ductal adenocarcinomas of the pancreas." (PMID 24498386, 2014). "Similarly, GNAS mutations are found frequently in IPMNs, whereas they are absent to rare in usual pancreatic ductal adenocarcinomas (PDACs)." (PMID 24312577, 2013). "Most reported alterations related to IPMNs and pancreatic ductal adenocarcinomas, including KRAS, GNAS, and BRAF mutations, are absent in ITPNs." (PMID 38539517, 2024).
gastric adenocarcinoma (10 papers, 2016 to 2025). "In another prior study, the GNAS mutation functioned as an alternative activator of the Wnt/beta-catenin signaling pathway in gastric adenocarcinoma." (PMID 35751785, 2022). "Compared with public data sets of conventional gastric adenocarcinoma (TCGA, Firehose Legacy), the frequency of GNAS mutation was significantly higher in GEN-FGML (7/34, 20.6% vs. 21/395, 5.3%, p < 0.01)." (PMID 34268625, 2021). "Since the frequency of GNAS mutation in common-type gastric adenocarcinoma is very low, we suggest that GNAS mutation was a characteristic genetic feature of GEN-FGML." (PMID 34268625, 2021). "Additional studies have shown that GNAS mutations occur frequently in gastric adenocarcinoma." (PMID 35486034, 2022). "More recent studies suggested that GNAS mutation might occur in a small subset of gastric adenocarcinomas of the fundic gland type as an alternative mechanism of activating the Wnt/beta-catenin signaling pathway." (PMID 27994902, 2016). "GNAS encodes a G protein alpha stimulatory subunit and is of interest given activating mutations have been proposed to mediate resistance to EGFR inhibitors and activate Wnt/β-catenin signaling pathways in gastric adenocarcinomas." (PMID 32158697, 2020). "According to the boxplot analysis, the mRNA levels of DOCK4, GNAS, TGFB1, SELE, and SMARCE1 demonstrated a considerably higher expression in gastric adenocarcinoma than in healthy controls." (PMID 37037466, 2023). "The average promoter methylation and mRNA expression levels of GNAS and MTERF1 were retrieved from 372 gastric adenocarcinoma cases." (PMID 35003353, 2021).